OPA1 (OPA1 mitochondrial dynamin like GTPase)
Diseases named in the same sentence as OPA1 in open-access papers (continued):
Sharing a sentence is not in itself a finding about the gene and the disease.
vitiligo (4 papers, 2021 to 2024). Generalized well circumscribed patches of leukoderma that are generally distributed over symmetric body locations and is due to autoimmune destruction of melanocytes. "This indicates that honokiol can prevent the apoptosis of vitiligo melanocytes under oxidative stress by activating the SIRT3/OPA1 pathway, offering a novel potential avenue for the treatment of vitiligo." (PMID 39119340, 2024). "Specific activation of SIRT3 by honokiol was capable to protect vitiligo melanocytes against oxidative stress via the regulation of OPA-1-dependent mitochondrial dynamics." (PMID 34938344, 2021). "In addition, in a further research, the authors confirmed that SIRT3 bound directly to OPA1 and activates it by deacetylation in vitiligo melanocytes under oxidative stress, suggesting that the OPA1 is a direct target of SIRT3." (PMID 35650472, 2022).
gastric cancer (3 papers, 2018 to 2024). A primary or metastatic malignant neoplasm involving the stomach. "NDUFA4 overexpression increases the MMP; decreases ROS levels; increases OPA1, p-Drp1, and PGC1α levels; promotes mitochondrial fusion, fission, and biogenesis; and inhibits apoptosis by regulating mitochondrial dynamics and biogenesis in gastric cancer cells." (PMID 39678510, 2024).
HCMV infection (3 papers, 2021 to 2023). "In the context of viral infection, OPA1 acetylation has been shown to be upregulated during human cytomegalovirus (HCMV) infection, as part of a global increase in the mitochondrial acetylome." (PMID 37238738, 2023). "SIRT3 deacetylates the fusion factor OPA1 to derepress its function, interfering with the fragmentation of mitochondria that is characteristic of HCMV infection." (PMID 37238738, 2023). "Given the knowledge that, in uninfected cells, SIRT3 has the ability to remove the OPA1 inhibitory acetylation at K931, we first investigated this residue in the context of HCMV infection." (PMID 33857259, 2021). "Meanwhile, HCMV infection upregulated the expression levels of MFN1 and OPA1 and overlapped with the M-AAA protease 1 homolog (OMA1)." (PMID 36939338, 2023). "The expression levels of mitochondrial fusion-related proteins including MFN1, OPA1, and OMA1 were increased in HCMV-infected THP-1 cells, as well as mitochondrial fusion after HCMV infection." (PMID 36939338, 2023). "Given our finding of altered OPA1 acetylation status and interaction with SIRT3 during HCMV infection, we examined its function by performing siRNA-mediated knockdown (siOPA1-KD) and over-expression (OE) studies." (PMID 33857259, 2021).
hearing disorder (3 papers, 2021 to 2024). A disorder characterized by the partial or complete loss of the ability to detect sounds due to damage to the ear structures or inability of the brain to properly interpret or process the auditory signals it receives from the anatomic structures of the ear. "Sensorineural hearing loss affects about 60% of OPA1 patients and AN has been proposed as the mechanism underlying the hearing disorder." (PMID 34940017, 2021). "The quantity of mitochondria in unmyelinated auditory nerve afferents is greater for large than small fibers, raising the possibility that the hearing disorder linked to OPA1 mutations may be specific for those auditory nerve fibers rich in mitochondria." (PMID 38334784, 2024).
Huntington disease (3 papers, 2010 to 2025). Huntington disease (HD) is a rare neurodegenerative disorder of the central nervous system characterized by unwanted choreatic movements, behavioral and psychiatric disturbances and dementia. "Additionally, research has indicated that in the brains of patients with Huntington’s disease (HD) postmortem, there is an increased expression of Drp1 and FIS1, while the expressions of Mfn1, Mfn2, and OPA1 are reduced." (PMID 41178992, 2025).
ischemic cardiomyopathy (3 papers, 2021 to 2023). Ischemic cardiomyopathy is a cardiomyopathy in which a weakness in the muscle of the heart due to inadequate oxygen delivery to the myocardium with coronary artery disease being the most common cause. "In support of this finding, Opa1 deficiency has been identified to correlate with I/R-mediated mitochondrial segregation and additionally, Chen and others reported decreased Opa1 levels in human hearts samples with ischemic cardiomyopathy." (PMID 36561366, 2022). "Nicorandil suppresses fission and boosts fusion by downregulating Drp1 and upregulating Opa1 and Mfn1 in ischemic cardiomyopathy rats." (PMID 37895224, 2023). "In ischemia-induced heart failure, OPA1 expression decreases, indicating that OPA1 plays an important role in ischemic cardiomyopathy." (PMID 34660720, 2021).
MELAS (3 papers, 2009 to 2023). "The mitochondrial diseases MERRF, and MELAS are cuased by mutations of the mitochondrial genome, but associated with abnormal proteolytically processing of OPA1." (PMID 19718456, 2009).
multiple sclerosis (3 papers, 2020 to 2024). A progressive autoimmune disorder affecting the central nervous system resulting in demyelination. "In light of this and the data reporting that OPA1 mutations are associated with multiple sclerosis-like symptoms, in this work, we analyzed OPA1 and its modulators in PBMCs of MS patients compared to HC." (PMID 32290388, 2020).
optic atrophy 1 (3 papers, 2011 to 2022). "It would therefore be of great interest to screen for OPA1 in a cohort of patients with isolated optic nerve hypoplasia to determine whether some patients harbour pathogenic mutations, or whether there is any association with specific polymorphic sequence variants." (PMID 21112411, 2011). "Here, we present the case of a 6-year-old male patient with severe early onset manifestation of OPA1-dependent optic atrophy 1 and his mother with subclinical manifestation of optic atrophy 1 carrying a postzygotic OPA1-mosaic." (PMID 35328032, 2022). "If OPA1 does exert a developmental influence on optic nerve head morphology, this could have important implications for other ocular disorders such as NTG and optic nerve hypoplasia." (PMID 21112411, 2011).
optic atrophy plus syndrome (3 papers, 2009 to 2025). "Recently, two groups reported that several OPA1 mutations cause “optic atrophy plus syndrome”." (PMID 19718456, 2009).
osteosarcoma (3 papers, 2017 to 2022). A usually aggressive malignant bone-forming mesenchymal neoplasm, predominantly affecting adolescents and young adults. "In the present study, we further confirmed that Tan IIA indeed reduced the levels of Mfn-1, Mfn-2 and Opa-1 and increased the levels of Drp-1 in both osteosarcoma 143B cells and 143B cell xenograft mice." (PMID 28106052, 2017).
Visual impairment (3 papers, 2017 to 2025). "SSBP1-related DOA shares similarities with OPA1-related DOA with an incomplete penetrance and an early childhood visual impairment." (PMID 34548540, 2021).
amyotrophic lateral sclerosis (2 papers, 2021 to 2022). Amyotrophic lateral sclerosis (ALS) is a neurodegenerative disease characterized by progressive muscular paralysis reflecting degeneration of motor neurons in the primary motor cortex, corticospinal tracts, brainstem and spinal cord. "CHCHD10 mutations associated with FTD/amyotrophic lateral sclerosis (ALS) have been shown that CHCHD 10 mutations impair ability to bind both OPA1 and mitofilin, and these mutants reduced the molecular weight of endogenous CHCHD10, mitofilin, and OPA1." (PMID 36061599, 2022).
brain injury (2 papers, 2021 to 2024). Acute and chronic (see also brain INJURIES, CHRONIC) injuries to the brain, including the cerebral hemispheres, CEREBELLUM, and brain STEM. "Regarding the effects of Mdivi-1 on neural mitochondrial fusion, the included studies showed that Mdivi-1 only increased neural outer membrane mitochondrial fusion (e.g., Mfn1 factor) but did not affect the neural inner membrane mitochondrial fusion (e.g., Opa1 factor) in I/R-induced brain injury." (PMID 35002619, 2021). "Taken together, our data suggest that EV-shuttled miRNA-382-5p may be a critical mediator of astrocyte-induced neurotoxicity under pathological conditions and that targeting miRNA-382-5p-OPA1 signaling has potential for clinical translation in the treatment of traumatic brain injury." (PMID 39617787, 2024).
cervical cancer (2 papers, 2019 to 2023). A primary or metastatic malignant neoplasm involving the cervix. "In addition, RNA sequencing data showed that Sp1 expression was positively correlated with the expression of Mfn1/2, Opa1, and Drp1 in tissues of cervical cancer patients." (PMID 37147632, 2023).
cholangiocarcinoma (2 papers, 2021 to 2023). A carcinoma that arises from the intrahepatic biliary tree (intrahepatic cholangiocarcinoma) or from the junction, or adjacent to the junction, of the right and left hepatic ducts (hilar cholangiocarcinoma). "Studies have shown that the downregulation of OPA1 or MFN1 inhibit the fusion process of HCC cell lines and cholangiocarcinoma (CCA) tumor organoids, inhibiting the growth of tumors in the body." (PMID 34804779, 2021).
chronic obstructive pulmonary disease (2 papers, 2023 to 2024). A chronic and progressive lung disorder characterized by the loss of elasticity of the bronchial tree and the air sacs, destruction of the air sacs wall, thickening of the bronchial wall, and mucous accumulation in the bronchial tree. "In support of this, Trp73 and OPA1 gene expression is decreased in chronic obstructive pulmonary disease (COPD) patients, a disease characterised by alterations in mitochondrial dynamics." (PMID 39516459, 2024). "This therefore represents a potential mechanism underpinning multiciliated cell loss in Trp73 null mice and may also be relevant in chronic obstructive pulmonary disease (COPD) pathogenesis, as we discovered that COPD patient cohorts display decreased Trp73 and OPA1 expression." (PMID 39516459, 2024).
colon cancer (2 papers, 2017 to 2021). "At the moment no data are available about the regulation of OPA1 in colon cancer, but it is reported that OPA1 is markedly decreased in hepato-cellular carcinoma along with a high mitochondrial fragmentation." (PMID 34067290, 2021).
COVID-19 (2 papers, 2021 to 2023). A disease caused by infection with severe acute respiratory syndrome coronavirus 2. "Genes impacting mitochondrial function include 31 of 37 in mitochondrial DNA and nuclear genes encoding mitochondrial proteins, including ten EDS-related (NDUFA-11/S3, OPA1, TYMP, etc.)and three COVID-19-related (STAT2, TLR3, NDUFAF7) genes." (PMID 37504295, 2023).
developmental delay (2 papers, 2013 to 2024). "Opa1 morphants were also significantly shorter (as measured by standard length) than MMC counterparts, which may indicate a developmental delay." (PMID 23516612, 2013).
diabetic neuropathy (2 papers, 2021 to 2023). A chronic, pathological complication associated with diabetes mellitus, where nerve damages are incurred due to diabetic microvascular injury involving small blood vessels that supply these nerves, resulting in peripheral and/or autonomic nerve dysfunction. "In a study investigating diabetic neuropathy, OPA1 was found to be significantly downregulated in motor neurons grown under HG conditions and in lumbar spinal cord tissues of rats with type 1 diabetes." (PMID 37563583, 2023). "In a study investigating diabetic neuropathy, Opa1 was found to be significantly downregulated in motor neurons grown in HG condition and in lumbar spinal cord tissues of type 1 diabetic rats." (PMID 34072974, 2021).
diabetic retinopathy (2 papers, 2021). "This study investigates whether reduced optic atrophy 1 (Opa1) level promotes apoptosis and retinal vascular lesions associated with diabetic retinopathy (DR)." (PMID 34072974, 2021).
emphysema (2 papers, 2021 to 2023). "Reduced expression of MFN1, MFN2 and OPA1 were also seen in alveolar epithelial cells in emphysema/COPD patients." (PMID 38110986, 2023). "In post-mortem analyses of lung tissue obtained from areas with mild and severe emphysema, impaired fusion characterized by a low quantity of OPA1 protein is correlated with disease severity." (PMID 33927681, 2021).
hereditary spastic paraplegia (2 papers, 2011 to 2014). Hereditary spastic paraplegias (HSP) comprise a genetically and clinically heterogeneous group of neurodegenerative disorders characterized by progressive spasticity and hyperreflexia of the lower limbs. "Motor evoked potentials performed in two patients showed electrophysiological abnormalities classical of hereditary spastic paraplegia, which has infrequently been reported in patients harbouring OPA1 mutations." (PMID 24727571, 2014). "Unexpectedly, OPA1 mutations were also identified in families previously labelled as having autosomal-dominant hereditary spastic paraplegia (HSP), and in individuals with visual failure complicated by a multiple sclerosis-like illness." (PMID 21112411, 2011).
intracerebral hemorrhage (2 papers, 2023 to 2025). A cerebrovascular disorder characterized by bleeding into one or both cerebral hemispheres including the basal ganglia and the cerebral cortex. "Furthermore, dysregulation of OPA1 has been linked to microglia activation, neuroinflammation and cognitive dysfunction, particularly in diseases such as retinal ischemia-reperfusion injury and intracerebral hemorrhage." (PMID 40354372, 2025). "Likewise, pterostilbene exhibits neuroprotective effects through suppressing microglial proinflammatory activities after intracerebral hemorrhage, which can be prevented by OPA1 knockout in microglia." (PMID 40354372, 2025).
kidney damage (2 papers, 2020 to 2025). "Melatonin improved nephropathy of ZDF rats and modulated their mitochondrial dynamics by reducing expression of Drp1 fission marker and increasing that of fusion markers, Mfn2 and Opa1." (PMID 32927647, 2020).
leprosy (2 papers, 2016 to 2022). Leprosy is a chronic infectious disease affecting primarily the skin and peripheral nervous system. "Most recently, we provided solid evidence to show that the OPA1 gene, encoding an mitochondrial inner membrane protein, was associated with leprosy susceptibility possibly by affecting mitochondrial function and antimicrobial pathways." (PMID 27876828, 2016).
Lung Squamous cell carcinoma (2 papers, 2018 to 2023). "The highest frequency of OPA1 alterations (29%) was found in patients with Lung Squamous cell carcinoma, where “amplification” was the predominant type." (PMID 37980164, 2023).
multiple sclerosis-like disorder (2 papers, 2020 to 2022). "Very interesting, mutations in OPA1 gene, have been associated with multiple sclerosis-like disorder." (PMID 32290388, 2020).
non-small cell lung carcinoma (2 papers, 2022 to 2024). A group of at least three distinct histological types of lung cancer, including non-small cell squamous cell carcinoma, adenocarcinoma, and large cell carcinoma. "Intriguingly, OPA1 deficiency disrupts mitochondrial dynamics, impeding respiratory function, and rendering tumor epithelial cells more sensitive to CD8+ T cell activity in non-small cell lung cancer." (PMID 38911373, 2024). "Thus, we aim to investigate the roles of OPA1 in mitochondria fusion and immune evasion of non-small cell lung cancer cells." (PMID 36573240, 2022). "More interestingly, OPA1 deficiency damaged mitochondrial dynamics and further blocked the respiratory function to increase the sensitivity of tumor epithelial to CD8+ T cells in non-small cell lung cancer." (PMID 36573240, 2022).
pancreatic cancer (2 papers, 2018 to 2025). "The following are possible reasons why pancreatic cancer cells show resistance to ferroptosis due to GPX4 inhibition: high expression of FSP1, low expression of OPA1, and impaired autophagy function." (PMID 39858464, 2025). "Although little is known about the role of GPX4 in pancreatic cancer, FSP1 or lack of OPA1 or autophagy dysfunction may suppress ferroptosis independently of GPX4, such that ML210 caused EMT suppression." (PMID 39858464, 2025).
progressive ataxia (2 papers, 2022). "One levodopa-treated patient developed dyskinesia, a single case harboring an OPA1 variant developed focal dystonia during disease course, and one POLG patient developed progressive ataxia." (PMID 34259909, 2022).
progressive external ophthalmoplegia (2 papers, 2013 to 2021). A mitochondrial myopathy characterized by slowly progressive paralysis of the levator palpebrae, orbicularis oculi, and extraocular muscles. "It was previously reported that up to 20% of patients with OPA1 mutations develop additional neuromuscular complications including deafness, ataxia, myopathy, peripheral neuropathy, and progressive external ophthalmoplegia." (PMID 23781337, 2013).
pulmonary arterial hypertension (2 papers, 2021 to 2024). Pulmonary arterial hypertension (PAH) is a group of diseases characterized by mean pulmonary artery pressure >20 mmHg and elevated pulmonary arterial resistance leading to right heart failure. "Recently, it has been demonstrated that BGP‐15 promotes mitochondrial fusion by activating optic atrophy 1 (OPA1), preventing mtROS induced fragmentation in multiple cell lines and in an in vivo model of pulmonary arterial hypertension (PAH)." (PMID 34337844, 2021). "In vitro and in vivo studies of pulmonary hypertension, a mitochondria-related disorder, have demonstrated that treatment with BGP-15 promotes mitochondrial fusion by activating optic atrophy 1 (OPA1)." (PMID 38602042, 2024).
renal fibrosis (2 papers, 2020 to 2024). A final common manifestation of a wide variety of chronic kidney diseases characterized by glomerulosclerosis and tubulointerstitial fibrosis. "findings revealed that the expression of the mitochondrial fission protein Drp1 was elevated, while the levels of mitochondrial fusion-related proteins Opa1 and Mfn2 were reduced in both in vivo and in vitro models of renal fibrosis." (PMID 39229866, 2024). "To address changes in mitochondrial dynamics in UUO-induced renal fibrosis, we evaluated the expression of mitochondrial Sirt3 and mitochondrial dynamin-related protein 1 (DRP1) and optic atrophy 1 (OPA1) expression after ureteral obstruction with vehicle or HKL treatment." (PMID 31936371, 2020).
retinal ischemia (2 papers, 2023 to 2024). A ischemic disease that involves the retina. "In a mice model of retinal ischemia and reperfusion injury, empagliflozin acts on mitochondrial dynamics upregulating the expression of Mfn1 and Opa1, reducing microglia-mediated neuroinflammation." (PMID 38892417, 2024). "Moreover, metformin protects against retinal ischemia/reperfusion injury through AMPK-mediated mitochondrial fusion (reversing the alteration in Mfn2 and OPA1 levels)." (PMID 38892417, 2024).
sarcoma (2 papers, 2023 to 2025). A usually aggressive malignant neoplasm of the soft tissue or bone. "We confirmed in murine sarcoma cells that the mutation of cysteine 403 abrogated OMA1 proteolytic activity toward the OPA1 protein and also possibly its autocatalytic activity." (PMID 37024121, 2023). "We therefore probed the involvement of the OMA1/OPA1 pathway in a mouse sarcoma model and tested whether the level of OMA1 and OPA1 expressions was associated with clinical outcome and immune variables in human soft tissue sarcomas (STS)." (PMID 37024121, 2023). "Our results in sarcoma suggest that the expression level of OMA1 and OPA1 varies significantly among sarcoma subtypes with complex genomics." (PMID 37024121, 2023). "The relevance of our findings in a mouse sarcoma model was questioned by exploring the levels of expression of the transcripts coding for OMA1 and OPA1 in a large series of STS with complex genomics, documented in various databases." (PMID 37024121, 2023).